MMP2 (matrix metallopeptidase 2)
Diseases named in the same sentence as MMP2 in open-access papers (continued):
Sharing a sentence is not in itself a finding about the gene and the disease.
breast cancer (continued). "A study demonstrated that exosome, rich in ECM degradation enzyme, transferred from MDA-MB-231 highly metastatic breast cancer cells to MCF-10A epithelial breast cancer cells (non-tumorigenic), leads to metastasis by increasing the expression of MMP-2 and MMP-9." (PMID 37046817, 2023). "Similarly, the effect of phytochemicals on MMP-2, MMP-9, and their tissue inhibitors (TIMPs) has been tested in breast cancer, with no alterations observed in vitro." (PMID 31921634, 2019). "Fluorescence microscopy studies using highly (A-673, rhabdomyosarcoma) and moderate (HT-1080, fibrosarcoma) MMP-2 expressing cell lines showed efficient binding of 48 to the MMP-2 positive cells while no binding to MMP-2 negative cells (MCF-7, breast cancer cells)." (PMID 31426440, 2019). "While roles for amoeboid/non-proteolytic ECM invasion have been described, MMP-2, in coordination with MMP-14, are key regulators of type I collagen degradation and cancer cell invasion through type I collagen encapsulating the growing breast cancer." (PMID 29874869, 2018). "Similarly, TGF-β-induced overexpression of MMP-2 and MMP-9 was mediated by p38 MAPK but not by ERK signaling in breast cancer cells." (PMID 23710144, 2013). "The strong MMP-2 mRNA expression correlated with a strong expression of proMMP-2 in the MDA-MB-468 and BT 20 cell lines, whereas the active form of MMP-2 could not be detected in any of the breast cancer cell lines tested." (PMID 19531263, 2009).
glioma (559 papers, 1998 to 2025). A benign or malignant brain and spinal cord tumor that arises from glial cells (astrocytes, oligodendrocytes, ependymal cells). "In this study, we evaluated the serum levels of GAL-1, -3, and − 8, along with ITGβ-1, HIF-1α, MMP-2, and − 9, as potential diagnostic markers in glioma." (PMID 40512281, 2025). "In oncology, chlorotoxin from Leiurus hebraeus provides a precedent: it binds selectively to tumor-associated receptors such as MMP-2 in gliomas and has been widely employed in tumor-targeting bioconjugates for both imaging and therapeutic applications." (PMID 41155199, 2025). "There is considerable evidence in the literature that MMP-2 and − 9 are associated with glioma by increasing cancer cell growth, migration, invasion, and angiogenesis." (PMID 40512281, 2025). "CCL5 (derived from glioma-associated microglia/brain macrophages [GAMs]) enhances glioma cell invasiveness through a novel calcium-dependent MMP2 signaling pathway." (PMID 39124881, 2024). "MMP2 is positively correlated with the invasion and migration of glioma cells, while MMP9 is implicated in cell invasion, migration and VM formation." (PMID 36459288, 2023). "In glioma, a HMGA2/GCN5 protein complex promoted histone acetylation in nucleosomes at AT-rich DNA sites, to cause gene activation of matrix metalloproteinase 2 (MMP2), a mediator of invasiveness in glioma, and conferring a poor prognosis." (PMID 36835656, 2023). "Knockdown of MMP2 using MMP2 siRNA caused suppression of cell proliferation in glioma 4910 and 5310 cells established from mouse xenografts of human glioma tumors." (PMID 36677584, 2023). "We additionally found that PLOD2 promoted the release of ECM-degrading MMP2—a mechanism associated with enhanced invasiveness and worse outcomes in different types of cancer, including glioma." (PMID 35682709, 2022). "In GMB, CCL5 (derived from glioma-associated microglia/brain macrophages [GAMs]) enhances glioma cell invasiveness through a novel calcium-dependent MMP2 signaling pathway." (PMID 36591235, 2022). "chemokine (C-C motif) ligand 5 (CCL5) was reported to modulate the migratory and invasive activities of human glioma cells in association with MMP2 expression." (PMID 35600367, 2022). "In vitro studies showed that Cltx binds to glioma cells without affecting normal cells; Cltx can bind endogenously to MMP-2 expressed in glioma cells, thus generating a loss of the gelatinase activity of the glioma and decreasing the expression of MMP2." (PMID 34795699, 2021). "MMP-9 and MMP-2 are associated with the integrity of the blood-brain barrier and have been shown to increase the invasiveness of human glioma cells." (PMID 32172480, 2021). "For instance, MMP2 is highly expressed in gliomas and it was recently associated with stimulation of vasculogenic mimicry in glioma cells." (PMID 34316711, 2021). "Some of the anti-glioma therapeutic potential of metformin appears to lie in its ability to downregulate fibulin-3 mRNA, causing suppression of MMP2 expression." (PMID 32911658, 2020). "A decisive role in glioma invasion is played by the gelatinases MMP-2 and MMP-9 and increased expression levels of MMP-2 is associated with glioma invasiveness." (PMID 30983966, 2019). "For example, it has been used to demonstrate that ionizing irradiation of PTEN null gliomas, U-251 MG and U-373 MG, determines an increased MatrigelTM invasion in association with an enhanced MMP-2 secretion." (PMID 29300332, 2018). "And, among these seven studies involved, there were six studies that also reported MMP-2 expression and glioma grade, so we also conducted a meta-analysis to investigate the association between MMP-2 expression and glioma grade among these six studies." (PMID 26729052, 2017). "This will cause the aberrant activation of STAT3/MMP2 signalling, which facilitated the migration and invasion of glioma cells." (PMID 28470949, 2017).
glioma (continued). "MMP-2 is highly expressed in multiple cancers including gliomas, and is associated with tumor invasion." (PMID 28915588, 2017). "In contrast, in a study testing the efficacy of bevacizumab in patients with recurrent high-grade gliomas, high MMP-2 plasma levels were associated with improved tumor control and survival." (PMID 28234925, 2017). "To explore the mechanism whereby TFF3 regulates glioma cell motility, we measured expression of the invasion- associated molecules MMP-2, finding that their protein levels significantly decreased after TFF3 knockdown in U87 and U251 cells." (PMID 29100347, 2017). "A total of 24 studies involving 1453 patients contained sufficient data for analyzing the association of MMP-2 expression with different WHO grades of gliomas." (PMID 26729052, 2017). "There were also evidences that high MMP-2 expression was associated with poor OS in patients with gliomas." (PMID 26729052, 2017). "Meanwhile, the expression levels of MMP9 and MMP2 were higher in high-risk patients compared with the low-risk group, suggesting gliomas had increased invasion potential in the former group." (PMID 27677590, 2016). "We further demonstrate that downregulation of MMP2 by WNK2 is associated with decreased levels of glioma cell invasion." (PMID 25596741, 2015). "Previous studies have shown the importance of IL-6 chemokine in the invasive behavior of gliomas and its association with MMP2." (PMID 25596741, 2015). "IDH1 mutation downregulated glioma cell proliferation by blocking the cell cycle, reduced the cell invasion ability via MMP-2 and MMP-9 downregulation and promoted the cell migration ability." (PMID 24520288, 2014). "Furthermore, high FLNC expression in glioma is associated with poor patient prognosis, increased invasion capacity, and elevated MMP2 expression." (PMID 39903772, 2025). "Moreover, in GBM, increased expression of MMP-2 and − 9 is reported to be associated with the malignancy of gliomas." (PMID 40512281, 2025). "The expression of MMP2 has been associated with glioma invasion." (PMID 38706905, 2024). "High invasiveness of gliomas is associated with the expression activity of MMP-2 and MMP-9." (PMID 39877386, 2024). "They found that high levels of MMP-2 in gliomas were associated with a poorer prognosis." (PMID 39684754, 2024). "It was previously reported that treatment with THC or CBD down-regulated the expression of major proteins associated with glioma tumor migration, in particular MMP-2, MMP-9, TIMP-4, and TIMP-1, even at low concentrations, which were insufficient to induce cell apoptosis." (PMID 35454080, 2022). "In addition to fibronectin, integrin-αvβ3 expression was found to be associated with the invasive phenotype of glioma cells and to colocalize with matrix metalloproteinase 2 (MMP-2)." (PMID 35631639, 2022). "Western blot was used to detect the changes of the expressions of VM-associated proteins in glioma cells, we found that the expression of MMP2, MMP9, and VE-cadherin were significantly reduced after overexpression of miR-651-3p and the anti-miR-651-3p group showed an oppisite effect." (PMID 33542193, 2021). "In addition, the ability of various glioma lines to migrate across a reconstituted basement membrane in vitro is associated with enhanced MMP2 expression." (PMID 34638718, 2021). "Furthermore, we probably assumed that [18F]-FP-chlorotoxin went through the destroyed brain-blood barrier and interacted with the glioma-specific ligands such as ClC-3 chloride channel, MMP-2, and αVß3 that caused the aggregation of chlorotoxin in the glioma." (PMID 30670934, 2018). "However, cholorotoxin, also binds to matrix metalloproteinase-2 (MMP2) resulting in reduced membrane-associated MMP2 activity and therefore inhibiting migration of glioma cells." (PMID 26010603, 2015).
glioma (continued). "Although the molecular mechanisms of CTX in glioma remains elusive, there is a general agreement that CTX binds specifically to a membrane complex of chloride channel-3 (ClC-3) and MMP-2, which may cause endocytosis of ClC-3/MMP-2 and a reduction of glioma invasiveness." (PMID 30486274, 2018). "Recent studies confirmed that IDH1 mutation is associated with better prognosis in patients with glioma by inducing cell cycle arrest in G1 phase, inhibiting cell proliferation, and reducing invasion ability, by reducing the levels of matrix metalloproteinases MMP2 and MMP9." (PMID 25695077, 2015). "SP also induces blebbing of glioma cell membranes and increases the expression of MMP-2 and MT1-MMP in glioma cells, resulting in migration and invasion of human glioma cells." (PMID 39941886, 2025). "Serum GAL-1, -3, -8, ITGβ-1, HIF-1α, MMP-2, and − 9 levels significantly differed between the glioma and healthy control groups." (PMID 40512281, 2025). "So far, in gliomas, increased expression of MMP-2 and MMP-9 has been described, correlating with the degree of tumor malignancy." (PMID 39352533, 2025). "This study discovered that metabolites derived from gut microbiota can suppress cell migration in glioma cells by reducing the expression of MMP2 and MMP9." (PMID 40873641, 2025). "This CTX-conjugated system represents a robust all-in-one platform for precisely diagnosing and treating MMP2-overexpressing gliomas." (PMID 40806525, 2025). "Gene therapy has emerged as a novel strategy to modulate MMPs’ expression in gliomas, particularly by using gene silencing techniques such as RNA interference (RNAi) to knock down MMP-2 or MMP-9 expression." (PMID 40265458, 2025). "Glioma cells are well known for their invasive potential, which is largely driven by matrix metalloproteinases (MMPs) such as MMP-2 and MMP-9." (PMID 41154863, 2025). "Immunohistochemistry revealed MMP-2 positivity in 38% of glioma cases and MMP-9 positivity in 81%, with MMP-9 also observed in endothelial cells, suggesting its role in angiogenesis." (PMID 40265458, 2025). "It has been reported that MMP-2 has an important role in glioma pathogenesis and can be used as a potential molecular marker for tumor progression." (PMID 40512281, 2025). "Immunohistochemical studies in glioma patients showed significantly higher expression of EphA2 (90.91%) and MMP-2 (86.36%) in high-grade tumors compared to low-grade cases." (PMID 41200151, 2025). "Evidence from prior studies show that FN1 enhances glioma development by interacting with integrin b, and activating MMP2/MMP9 to accelerate the invasion and metastasis of cancer cells." (PMID 41199745, 2025). "The findings from these studies suggest that CCL5 modulates the migratory and invasive capabilities of human glioma cells in conjunction with MMP2 expression." (PMID 40620486, 2025). "Preclinical studies using siRNA or shRNA targeting MMP-2 or MMP-9 have shown that reducing these MMPs’ expression diminishes glioma cell invasion and enhances the response to chemotherapeutic agents." (PMID 40265458, 2025). "For instance, chlorotoxin, a peptide from scorpion venom, has demonstrated the ability to bind selectively to matrix metalloproteinase-2 (MMP-2), a protein overexpressed in glioma cells." (PMID 40864047, 2025). "The first evidence was the high expression of MMP-2 in astrocytes when they were cultured with glioma cells, and the invasive nature of glioma was attributed to it." (PMID 41356146, 2025). "In particular, MMP‐2 has an increased activity correlated with the grade of glioma and is considered an attractive target for GBM therapy." (PMID 40556034, 2025). "MMP2 is known to influence glioma angiogenesis and enhance tumour proliferation and invasion; thus, it is a key biomarker for the response to antivascular therapy." (PMID 39903772, 2025).
glioma (continued). "Chlorotoxin (CTX) from Leiurus hebraeus binds glioma-specific chloride channels and MMP-2, inhibiting metastasis and enhancing blood–brain barrier penetration for drug delivery." (PMID 41155199, 2025). "CTX specifically targets matrix metalloproteinase-2 (MMP-2) on glioma cells, mediating receptor-driven internalization." (PMID 40733120, 2025). "MMP-2, MMP-9, and MMP-14 are particularly implicated in BBB degradation in gliomas, where their activity weakens tight junctions between endothelial cells and facilitates tumor invasion into the brain parenchyma." (PMID 40265458, 2025). "Further studies on MMP-2 inhibitors, such as the selective gelatinase inhibitor SB-3CT, revealed a reduction in glioma cell invasion and a decrease in angiogenesis by preventing endothelial cell migration, a critical process in tumor vascularization." (PMID 40265458, 2025). "Another study demonstrated that glioma invasion was driven by MMP-2 activity, which was significantly higher in glioma cell lines than in non-invasive glial cells." (PMID 40265458, 2025). "Chlorotoxin (ClTx), an animal venom-derived peptide initially characterized as a Cl− channel blocker, specifically interacts with MMP-2 and exerts anti-invasive effect in glioma." (PMID 41155636, 2025). "MRI features such as peritumoral edema, contrast enhancement, and tumor size also correlated with EphA2 and MMP-2 expression, reinforcing their role in glioma invasiveness." (PMID 41200151, 2025). "In glioma, it has been reported that MMP-2 expression correlates with high pathological grade and increased invasiveness, thus representing a negative prognostic factor." (PMID 40724848, 2025). "Employing quantitative real-time polymerase chain reaction, we ascertained the relative expression levels of miR-760 and MMP2 in glioma cell lines." (PMID 38706905, 2024). "A bioinformatic analysis tool and a dual-luciferase activity reporter experiment were used to identify MMP2 as a potential target of miR-760 in glioma cells." (PMID 38706905, 2024). "Wnt5a modulates the synthesis of matrix metalloproteinase-2 (MMP-2), thereby enhancing glioma cell migration." (PMID 38886806, 2024). "Collectively, these findings posit that miR-760 exerts a restraining influence on glioma growth by orchestrating the upregulation of miR-760 along the miR-760/MMP2 axis." (PMID 38706905, 2024). "For example, the literature has shown that c-Cbl, a multifunctional adaptor and an E3 ubiquitin ligase, promotes glioma invasion by upregulation of MMP2." (PMID 39458959, 2024). "The expression levels of tumor invasion and EMT‐related molecules, including MMP2, N‐cadherin, Snail, and Vimentin, were significantly decreased in the knockdown glioma groups." (PMID 37545464, 2024). "It has been shown that glioma tissue is one of the main sources of matrix metalloproteinase (mostly MMP-2 and MMP-9) as compared to normal brain tissue." (PMID 39682088, 2024). "BmK CT and its radiolabeled derivatives, 125I-BmK CT and 131I-BmK CT, inhibited the expression of MMP-2, subsequently diminishing the invasiveness of glioma cells." (PMID 39770577, 2024). "In vitro studies confirmed that ClTx reduced glioma cell migration by MMP-2 deactivation and reduction in Cl− ions expression, thus preventing glioma cells from shrinking and migration." (PMID 39361208, 2024). "MMP-2 and MMP-9 are extracellular proteolytic enzymes participating in the invasion and tumor progression of glioma, and our results showed significant P129-induced MMP-2 and MMP-9 inhibition." (PMID 38184514, 2024). "CTX decreases the expression of MMP-2 on the cell surface through endocytosis and inhibits its enzymatic activity, thereby exhibiting anti-invasion effects on glioma cells." (PMID 39770577, 2024). "MMP-2 was shown to modulate glioma cell migration by disrupting the composition of the extracellular matrix and altering the expression of cell surface adhesion receptors." (PMID 38164487, 2024).